ICAM1 (intercellular adhesion molecule 1)
Diseases named in the same sentence as ICAM1 in open-access papers (continued):
Sharing a sentence is not in itself a finding about the gene and the disease.
Hypervolemia (1 paper, 2010). An increase in the amount of intravascular fluid, particularly in the volume of the circulating blood. "Furthermore, hypervolemia was associated with alveolar and endothelium damage as well as increased IL-6, VCAM-1 and ICAM-1 mRNA expressions in lung tissue; 2) RMs reduced alveolar collapse regardless of volemic status." (PMID 20546573, 2010). "Furthermore, hypervolemia was associated with alveolar and endothelium damage as well as increased mRNA expression of IL-6, VCAM-1 and ICAM-1 in lung tissue." (PMID 20546573, 2010). "We observed that: 1) hypervolemia increased lung W/D ratio with impairment of oxygenation and Est,L, and was associated with alveolar and endothelial cell damage and increased IL-6, VCAM-1, and ICAM-1 mRNA expressions; and 2) RM reduced alveolar collapse independent of volemic status." (PMID 20546573, 2010).
inflammatory skin disease (1 paper, 2016). Inflammatory skin disorders covers a broad category that includes many conditions ranging in severity, from mild itching to grave medical health complications These disorders are common in people of all ages and races. "Within a month, the RAF1Δep animals developed an inflammatory skin disease characterized by K6 and ICAM1 expression in the epidermis, by the presence of activated dermal mast cells and by an increase in TSLP." (PMID 27431613, 2016).
internal carotid artery stenosis (1 paper, 2025). Carotid stenosis is a narrowing or constriction of the inner surface (lumen) of the carotid artery, usually caused by atherosclerosis. "Transcriptomic analysis reveals the molecular mechanism by which early stent placement improves neurovascular unit damage and cerebral microcirculatory disorder induced by severe internal carotid artery stenosis through ICAM1 regulation." (PMID 41404041, 2025).
ischemic cardiomyopathy (1 paper, 2022). Ischemic cardiomyopathy is a cardiomyopathy in which a weakness in the muscle of the heart due to inadequate oxygen delivery to the myocardium with coronary artery disease being the most common cause. "Previous research has linked single nucleotide polymorphisms (SNPs) in the ICAM-1 gene to an increased risk of developing ischemic cardiomyopathy (ICM); however, a diagnostic model of ICM according to the ICAM-1 variant has not yet been developed." (PMID 36440000, 2022).
keratoconjunctivitis (1 paper, 2018). Inflammation of both the cornea and the conjunctiva. "Increased expression of intercellular adhesion molecule 1 (ICAM-1) and lymphocyte function-associated antigen 1 (LFA-1) in keratoconjunctivitis, causing homing and antigen presentation of T-cells, is known to be important." (PMID 30217034, 2018).
Klebsiella pneumonia (1 paper, 2023). An pneumonia caused by infection with Klebsiella. "Established Klebsiella pneumonia increased mRNA concentrations of Collagen I and VI and ICAM 1 and lung myeloperoxidase." (PMID 37469663, 2023).
labyrinthitis (1 paper, 2022). Inflammation of the inner ear. "This expression pattern is similar to enhanced ICAM1 immunoexpression during cochlear inflammation resulting from noise exposure, labyrinthitis, immune response, and physical trauma." (PMID 35563572, 2022).
laryngeal carcinoma (1 paper, 2025). Carcinoma that arises from the laryngeal epithelium. "PXN, ITGB1, ISG15, SLC2A1 and ICAM1 are regarded as potential therapeutic targets for HPV-positive laryngeal cancer." (PMID 40821990, 2025). "ISG15, ITGB1, PXN, SLC2A1 and ICAM1 are expected to become potential therapeutic targets for HPV-positive laryngeal cancer." (PMID 40821990, 2025). "Key genes like CDC42, PXN, ITGB1, PGK1, SLC2A1, ISG15 and ICAM1, affected by HPV, display distinct functional alterations and complex correlations in laryngeal cancer progression." (PMID 40821990, 2025).
leiomyoma (1 paper, 2023). A well-circumscribed benign smooth muscle neoplasm characterized by the presence of spindle cells with cigar-shaped nuclei, interlacing fascicles, and a whorled pattern. "Many proteins such as F3, WNT2, CDH1, and LIF shown in the protein–protein interaction networks are well known in leiomyoma pathogenesis, and others, such as ICAM1, CXCL8, CCL2, and NANOG are novel and require further investigation." (PMID 36835153, 2023).
Leukocyte adhesion deficiency type I (1 paper, 2006). Leukocyte adhesion deficiency type I (LAD-I) is a form of LAD (see this term) characterized by life-threatening, recurrent bacterial infections. "To corroborate the importance of the ICAM-1— LFA-1 interaction, we performed transmission experiments to LFA-1 negative leukocytes from Leukocyte Adhesion Deficiency type 1 (LAD-1) patients." (PMID 17078873, 2006).
lipodystrophy (1 paper, 2021). A congenital or acquired disorder characterized by abnormal loss or redistribution of the adipose tissue in the body. "Age had the strongest positive association with lipodystrophy and also positively correlated with several inflammatory markers, including LBP, CRP, IL-6, ICAM-1, and serum amyloid A (SAA)." (PMID 34006628, 2021).
listeriosis (1 paper, 2022). A bacterial infection caused by Listeria monocytogenes. "Upregulation of P-selectin and ICAM-1 during experimental murine listeriosis could play an important role in the recruitment of leukocytes, especially to the liver, lymphoid organs, and central nervous system." (PMID 35195181, 2022).
lumbar disc herniation (1 paper, 2015). "In previous studies, ICAM-1 was identified on human lumbar disc herniation tissue." (PMID 25993467, 2015).
Lymphatic Metastasis (1 paper, 2023). Transfer of a neoplasm from its primary site to lymph nodes or to distant parts of the body by way of the lymphatic system. "The expression of the MET and ICAM1 in the lymphatic metastasis group were significantly higher than that in the non-metastatic group and the normal group (P<0.001)." (PMID 37274228, 2023).
malignant glioma (1 paper, 2015). A grade III or grade IV glioma arising from the central nervous system. "Furthermore, the expression levels of the migration-related molecules VEGF and ICAM-1 were also increased in malignant gliomas." (PMID 26473373, 2015).
meningioma (1 paper, 2024). A generally slow growing tumor attached to the dura mater. "Meningiomas Group: ICAM-1, E-Selectin, and MMP-9 were the most expressed markers, while PAI-1 and VCAM-1 exhibited less expression." (PMID 38306519, 2024).
Myelopathy (1 paper, 2019). Myelopathy is an descriptive term, referring to pathology leading to a neurologic deficit related to the spinal cord. "However, IFX treatment did not influence the level of soluble ICAM-1 under this condition, and was therefore estimated to play no role in further accelerating HTLV-1 infection or upregulation, which is consistent with results from an in vitro investigation of HTLV-1-associated myelopathy." (PMID 31620105, 2019).
myoepitheliomas (1 paper, 2020). "Finally, ICAM-1 was absent in oncocytoma, whereas the two cases of myoepitheliomas showed a heterogeneous positivity." (PMID 33372636, 2020).
myositis (1 paper, 2025). "The hPBMC mice exhibit elevated serum levels of creatine kinase and aspartate transaminase, markers of myositis, and increased expression levels of myositis-related genes, such as vascular cell adhesion molecule 1, intercellular adhesion molecule 1, and serum amyloid A1, in muscle tissues." (PMID 39810259, 2025).
Neisseria meningitidis infection (1 paper, 2025). "ICAM-1 and CD44 are massively recruited to bacterial adhesion sites during Neisseria meningitidis infection, together with the ERM proteins (ezrin), to regulate host inflammatory response by blocking the transendothelial migration of leukocytes." (PMID 41440381, 2025).
neovascular age related macular degeneration (1 paper, 2009). "Of relevance, ICAM-1 has been detected in vitro in cultured glia and neurons as well as in vivo in the external limiting membrane of the retina and photoreceptor aggregates in patients with neovascular age related macular degeneration." (PMID 19626134, 2009).
Niemann-Pick disease (1 paper, 2020). A group of inherited, severe metabolic disorders in which sphingomyelin accumulates in lysosomes in cells. "Anti-ICAM-1-coated nanocarriers have also been used to target recombinant proteins, such as human acid sphingomyelinase to ICAM-1-positive cells, including activated endothelial cells and Niemann–Pick disease patient fibroblasts." (PMID 33304924, 2020).
non-Hodgkin lymphoma (1 paper, 2020). Distinct from Hodgkin lymphoma both morphologically and biologically, non-Hodgkin lymphoma (NHL) is characterized by the absence of Reed-Sternberg cells, can occur at any age, and usually presents as a localized or generalized lymphadenopathy associated with fever and weight loss. "Previous studies reported that lower ICAM-1 expression correlated with inferior prognosis in non-Hodgkin's lymphoma before rituximab era." (PMID 33288735, 2020).
ocular infection (1 paper, 2018). "Microarray analysis and qPCR did not detect significant changes in ICAM1, CYR61, or PTX3 transcript levels in TLR4−/− following infection, suggesting the importance of TLR4 in eliciting a neutrophil response and complement activation following B. cereus ocular infection." (PMID 29661181, 2018).
Onset (1 paper, 2022). The age group in which disease manifestations appear. "In a study from our centre of adolescent participants with early-onset psychosis, reduced levels of PSEL and VCAM-1 and no significant alterations of ICAM-1, MadCAM-1, JAMA or NCAD, were found." (PMID 35856063, 2022).
Opportunistic infection (1 paper, 2022). An infection that is caused by a pathogen that would generally not be able to cause an infection in a host with a normal immune system. "This suggests that the interaction between ICAM-1 on vaginal epithelial cell and its ligands from C. albicans could be a crucial step for the opportunistic infection caused by C. albicans." (PMID 35295335, 2022).
oral lichen planus (1 paper, 2013). Oral lichen planus is a chronic inflammatory oral condition of unknown aetiology characterized by T-cell-mediated chronic immune response and abnormal epithelial keratinization cycle. "In conclusion, higher expression of VCAM1 and ICAM1 were seen in oral lichen planus compared to normal oral mucosa which appears to be involved in pathogenesis of oral lichen planus." (PMID 24551788, 2013). "VCAM1 and ICAM1 expression significantly increased compared to normal mucosa in oral lichen planus according to the percentage of stained cells (p=0.000& p=0.000, Mann-Whitney test)." (PMID 24551788, 2013). "The aim of this study is the immunohistochemical evaluation of VCAM1 and ICAM1 in oral lichen planus and to compare these two markers with normal mucosa for evaluation of angiogenesis." (PMID 24551788, 2013). "In the current research, higher expression of ICAM1 has been detected in oral lichen planus, implicating its role in the inflammation and pathogenesis of the disease." (PMID 24551788, 2013). "Regarding the results, it seems that high expression of VCAM1 and ICAM1 is related to oral lichen planus." (PMID 24551788, 2013). "Mann-Whitney test was used to compare the percentage of stained cells in oral lichen planus and normal mucosa, and the results showed significant increase in VCAM1 and ICAM1 expression in oral lichen planus compared to normal mucosa (p<0.001 and p<0.001)." (PMID 24551788, 2013).
ovarian clear cell cancer (1 paper, 2024). An invasive malignant neoplasm that arises from the ovary and is characterized by a predominance of clear and hobnail malignant epithelial cells. "The lipophagy-ICAM-1 pathway induced under tumor-like stress conditions contributes to the progression of ovarian clear cell carcinoma, making the lipophagy pathway a potential therapeutic target for this aggressive cancer type." (PMID 39165945, 2024).
Pancytopenia (1 paper, 2017). An abnormal reduction in numbers of all blood cell types (red blood cells, white blood cells, and platelets). "Repeated administration of non-viable E.coli to WT mice resulted in a peripheral pancytopenia, but reductions in T and B cell numbers was ameliorated in Icam-1 KO mice." (PMID 28733045, 2017).
paralytic poliomyelitis (1 paper, 2023). "The C-CAVs likely gave rise to the PVs; CAV21 causes paralytic poliomyelitis in human ICAM1-transgenic mice, analogous to the PVs in human CD155-transgenic mice." (PMID 37962360, 2023).
pediatric tumors (1 paper, 2025). "In addition, the increased expression of ICAM-1 promoted the enhanced formation of NK cell-BC cell conjugates, consistently with previous findings showing that ICAM-1 plays a critical role in supporting NK cell-functions in the context of pediatric tumors." (PMID 41102150, 2025).
peripheral vascular disease (1 paper, 2015). Any disorder affecting blood flow through the veins or arteries outside of the heart. "The fact that soluble VCAM-1, but not ICAM-1, remained the only predictor of c-IMT in hypertensive patients with peripheral vascular disease supports this hypothesis." (PMID 26066045, 2015).
peritoneal adhesion (1 paper, 2019). "ICAM-1 is expressed in migratory EC53, and is linked to increased peritoneal adhesion in endometriosis." (PMID 31391455, 2019).
plasma cell disorders (1 paper, 2024). "Ultimately, the NGS analyses successfully identified two novel antibodies, CD38 and ICAM-1, which are potential candidates for the treatment of plasma cell disorders." (PMID 39631781, 2024).
pneumococcal infection (1 paper, 2021). Infections with bacteria of the species streptococcus pneumoniae. "Furthermore it should also be noted that ICAM-1 may have other roles aside from cellular recruitment such as bacterial killing as seen in a pneumococcal infection model (although migration into the alveolar space was not assessed) or activating NK cells to induce cell lysis during infection." (PMID 34484188, 2021).
poliomyelitis (1 paper, 2016). An acute infectious disorder that affects the nervous system. "This virus revealed to be able to invade the central nervous system by retrograde axonal transport and caused poliomyelitis in ICAM-1 transgenic mice In humans, CVA21 was detected in stool samples of patients with AFP." (PMID 26761027, 2016).
pollen allergy (1 paper, 2022). "We envision that Nb44 could be used to engineer allergen/ICAM-1-specific heterodimers to develop bispecific nanobodies for topical treatments of pollen allergy." (PMID 36439110, 2022).
pressure ulcers (1 paper, 2023). "We also found at T4 a slight increase in ICAM-1, which has been reported in SCI patients with pressure ulcers, pointing towards changes in cellular adhesion linked with spinal injury." (PMID 37446303, 2023).
primary immunodeficiencies (1 paper, 2023). "Variants in ICAM1 and INPP5D are reported to be associated with primary immunodeficiencies in HGMD." (PMID 37080976, 2023).
protozoal infections (1 paper, 2023). "Notably, ICAM1, TLR2, and FN1 were associated with bacterial, viral, and protozoal infections, a conclusion also observed in numerous additional studies." (PMID 37233676, 2023).
Psoriasiform dermatitis (1 paper, 2020). A skin abnormality characterized by redness and irritation, with thick, red skin that displays flaky, silver-white patches (scales). "We further investigated the effects of IL-36R inactivation on induction of ICAM-1 by HDMEC using an IMQ-induced psoriasiform dermatitis mouse model." (PMID 32352958, 2020).
pulpitis (1 paper, 2020). Inflammation of the dental pulp. "In addition to investigating the possible regulatory mechanisms of DEGs, we screened key genes as biomarker candidates for the diagnosis of pulpitis, including PTPRC, CD86, CCL2, IL6, TLR8, MMP9, CXCL8 and ICAM1." (PMID 33046027, 2020).
renal dysfunction (1 paper, 2021). "Notably, in cirrhotic ascitic rats from our study, chronic pioglitazone pre-treatment attenuated LPS-induced TNFα/NFκB-mediated acute on chronic renal dysfunction by suppressing renal IL-6, ICAM-1 and VCAM-1." (PMID 34831270, 2021).
respiratory syncytial virus infection (1 paper, 2013). "Increased adhesion molecules expression, such as ICAM-1 and VCAM-1, on A549 lung epithelial cells was reported upon respiratory syncytial virus infection." (PMID 24073006, 2013).
retinal disease (1 paper, 2008). "ICAM1 (intercellular adhesion molecule 1) is commonly associated with retinal disease states, as adhesion molecules are produced by vascular endothelial cells are induced during the proliferative stages of DR." (PMID 18554398, 2008).
retinal vasculitis (1 paper, 2022). Inflammation of the retinal vasculature with various causes including infectious disease; lupus erythematosus, systemic; multiple sclerosis; behcet syndrome; and chorioretinitis. "In BD patients presenting retinal vasculitis, however, only sE-selectin and s-ICAM-1 serum levels were significantly increased." (PMID 35008929, 2022).
retinal vein occlusion (1 paper, 2021). An occlusion of the retinal vein. "ICAM-1 is an adhesion molecule and promotes leukostasis in ischemic retinopathies such as retinal vein occlusion and diabetic retinopathy, in which inflammation plays a crucial role." (PMID 34321574, 2021). "Because intraocular levels of ICAM-1 are increased in other retinal disorders, such as retinal vein occlusions, future studies need to enroll a control group without ischemic retinal disorders." (PMID 34321574, 2021).
rosacea (1 paper, 2021). A chronic erythematous skin disorder that affects the face. "Moreover, studies demonstrated the potential relationship between MLT target genes (MMP9, CCND1, EGFR, ICAM1, PTGS2, and SERPINE1) and rosacea-related key genes (IL-6, IL-1β, IFNγ, IL-17, and TNF-α)." (PMID 34899707, 2021).
Salmonella Infections (1 paper, 2014). Infections with bacteria of the genus SALMONELLA. "Earlier data from a murine model suggested a TNFα- and IL-1-mediated expression of ICAM-1 on hepatocytes following Salmonella infection." (PMID 24932686, 2014).
schwannoma (1 paper, 2024). A benign, usually encapsulated slow growing tumor composed of Schwann cells. "Schwannomas Group: ICAM-1 was the most expressed, with E-Selectin, MMP-9, PAI-1, and VCAM-1 showing moderate expression." (PMID 38306519, 2024).
scrub typhus (1 paper, 2020). Scrub typhus is a rare dust mite-borne infectious disease caused by the Orientia tsutsugamushi bacterium and characterized clinically by an eruptive fever which is potentially serious. "Our observed ICAM1 and IL-8/CXLC8 up-regulation in infected human EC cultures were consistent with other reported studies of scrub typhus patients." (PMID 32119672, 2020).
selenium deficiency (1 paper, 2014). A nutritional deficiency disease resulting from inadequate selenium levels in the body, which can lead to impaired function of selenoproteins essential for antioxidant defense and thyroid hormone metabolism. "DNA methylation profile between Keshan Disease patients and normal individuals showed that selenium deficiency decreased methylation of CpG islands in promoter regions of TLR2 and ICAM1, in agreement with results from in vivo and in vitro models of the disease." (PMID 25268836, 2014).
septic arthritis (1 paper, 2024). "Deficiency in intercellular adhesion molecule 1 (ICAM-1) or treatment with anti-ICAM-1 antibodies resulted in a less severe form of septic arthritis but increased mortality." (PMID 38410388, 2024). "This highlights the dual role of ICAM-1 in septic arthritis: while it provides protection against lethal sepsis, it concurrently exacerbates the development of septic arthritis." (PMID 38410388, 2024).
severe acute respiratory syndrome (1 paper, 2024). A viral respiratory infection caused by the SARS coronavirus. "Differences in sequelae symptoms, cardiovascular biomarkers (VCAM-1, ICAM-1, and ACE2), Severe Acute Respiratory Syndrome Coronavirus 2 neutralization antibodies (SARS-CoV-2 nAb) and cytokines (IFN-γ, IL-6, and IL-17) were analyzed between the two groups." (PMID 39669584, 2024).